PIK3CA (phosphatidylinositol-4,5-bisphosphate 3-kinase catalytic subunit alpha)
Diseases named in the same sentence as PIK3CA in open-access papers (continued):
Sharing a sentence is not in itself a finding about the gene and the disease.
breast cancer (continued). "As with EGFR mutations in advanced NSCLC and PIK3CA mutations in advanced breast cancer, strong concordance has been found between the RAS mutational status of CRC tissue and matching plasma in patients with advanced CRC." (PMID 35055414, 2022). "The combination of a graphene oxide screen printed electrode (GPHOXE) and dCas9 proteins and sgRNA was used to detect a PIK3CA E542K mutation in the ctDNA of patients with breast cancer." (PMID 36551512, 2022). "The most common genetic event in ER+ breast cancer is mutation of PIK3CA, the gene encoding the p110α catalytic subunit of phosphoinositide 3-kinase alpha (PI3Kα), which occurs in up to 40% of ER+ breast cancers." (PMID 36612130, 2022). "Given the role of PIK3CA as a prognostic and therapeutic target in breast cancer, tumors were also analyzed to assess the PIK3CA mutational status." (PMID 35740668, 2022). "In particular, PIK3CA N1044K is a known oncogenic mutation that is targetable in human breast cancer by an FDA-approved drug." (PMID 35471999, 2022). "According to preliminary data, approximately 27% of breast cancer patients have PIK3CA mutation, more than 20% of endometrial cancer patients have PIK3CA mutation, and approximately 14% of colon cancer patients have PIK3CA mutation." (PMID 35277182, 2022). "Lately, the Food and Drug Administration (FDA) approved testing of PIK3CA mutations in breast cancer patients using breast tumor tissue or circulating tumor DNA, isolated from plasma specimens." (PMID 35164019, 2022). "In this study, we proposed a DCNN-ImResNet for the automated identification of PIK3CA mutations in breast cancer based on US images." (PMID 35719907, 2022). "It is estimated that approximately 40% to 50% of patients with hormone receptor-positive/HER2− breast cancer have aberrant activation of PIK3CA (encoding the p110α isoform of PI3K), which is closely correlated with ET resistance." (PMID 36091147, 2022). "The most frequent mutations are in PIK3CA, expecially in exon 9 and 20, identified from tumor tissue and/or circulating DNA, in all breast cancer subtypes." (PMID 35610639, 2022). "Somatic mutations in PIK3CA are present in ~40% breast cancers (BC); their detection in hormone receptor (HR)+/HER2− tumors allows for selecting patients with advanced disease eligible for PIK3CA targeting with alpelisib." (PMID 36428975, 2022). "Activation of oncogenes as PIK3CA and loss of tumor suppressors are thought to be early breast cancer events." (PMID 35164019, 2022). "A performance summary of the ImResNet model and other models in identifying PIK3CA mutations of breast cancer." (PMID 35719907, 2022). "PIK3CA mutations of the helical domain has been reported in up to 26% of breast cancers, E542K and E545K being the most prevalent point mutations and were reported in 20% and 11% of cases, respectively." (PMID 35317488, 2022). "On the basis of data from the phase III SOLAR-1 trial, the therascreen® PIK3CA RGQ PCR kit was granted FDA approval for the detection of PIK3CA mutations in plasma or tumor tissue in patients with advanced-stage (HR)+/HER2 − breast cancer." (PMID 35307037, 2022). "In ER+ breast cancer cells harboring PIK3CA and PTEN mutations, treatment with a PI3K/mTOR inhibitor resulted in increased RTK-mediated signaling and upregulation of EGFR/ERK/p-BadS112." (PMID 35053443, 2022).
breast cancer (continued). "Studies have confirmed that the activating mutation of PIK3CA is a carcinogenic mechanism related to the excessive activation of this pathway, and this gene mutation is distributed in various breast cancer subtypes." (PMID 35311116, 2022). "Alpelisib is a PI3K alpha specific inhibitor for the treatment of breast cancer with a PIK3CA mutation after disease progression." (PMID 35785151, 2022). "Capivasertib (AZD5363), an ATP-competitive Akt inhibitor has demonstrated anti-tumor activity in a xenograft model of PIK3CA-mutated breast cancer." (PMID 36046843, 2022). "The proposed ImResNet model has the ability to identify PIK3CA mutations in breast cancer based on US images." (PMID 35719907, 2022). "So far, it is the first study of US images based on deep learning for the identification of PIK3CA mutations in breast cancer." (PMID 35719907, 2022). "The selective PI3Kα inhibitor alpelisib combined with fulvestrant is permitted to treat breast HR‐positive, HER2‐negative breast cancer harboring PIK3CA mutation after an endocrine‐based regimen." (PMID 36254250, 2022). "PIK3CA, the gene which encodes the p110α subunit of PI3Kα is found to be mutated in approximately 30% of all breast cancers, resulting in increased retention at the plasma membrane and increased catalytic activity." (PMID 36045910, 2022). "Nevertheless, the prognostic and predictive value of the PIK3CA mutation status as a biomarker for early breast cancer is discussed controversially for BC subgroups with respect to hormone receptor and HER2 expression." (PMID 36279023, 2022). "So far, reports on the somatic genomic landscape of breast cancer state that PIK3CA mutations are less frequent in young women when compared with older ones." (PMID 36011273, 2022). "In previous clinical studies in Asia, TAS-117 has shown clinical efficacy in PIK3CA-mutated endometrial and ovarian cancers, in breast cancer cases harboring PIK3CA or AKT1 mutations, and in patients with ovarian clear cell carcinoma." (PMID 36039910, 2022). "Alpelisib is currently approved for use in PIK3CA-mutated, hormone receptor positive advanced breast cancer." (PMID 35225964, 2022). "It selectively inhibits p110α and blocks the PI3K signaling pathway, thereby suppressing the growth of breast cancer cells carrying PIK3CA mutations." (PMID 35778737, 2022). "The loss of PTEN and PIK3CA gene mutations are the most common genomic events seen in human malignancies, including breast cancer." (PMID 35887191, 2022). "Several studies on neoadjuvant treatment of patients with HER2-positive breast cancer have shown that PIK3CA mutations can be associated with lower pCR rates, more marked in estrogen receptor (ER)-positive cancer, and shorter disease-free survival (DFS)." (PMID 35740668, 2022). "Using the ERBB2 S310F and PIK3CA H3140R mutations in breast cancer as examples, this method was validated in a synthetic plasmid template and xenograft mouse blood samples, with a sensitivity of 96.6%." (PMID 36551512, 2022). "In this study, we describe the prevalence of the three most common PIK3CA-mutations in subgroups of a breast cancer cohort and its association with clinical, histopathological characteristics and survival." (PMID 36279023, 2022). "As one of the most common mutated genes in breast cancer, PIK3CA plays an essential role in both the development and progression of breast cancer." (PMID 35719907, 2022).
breast cancer (continued). "The real overall somatic mutation rate of PIK3CA is 26.7% when testing the three most common hot spots H1047R, E545K, and E542K in a representative cohort of patients with early breast cancer." (PMID 36279023, 2022). "In contrast, another study of baseline ctDNA of advanced breast cancer patients treated with palbociclib or ribociclib found that patients with PIK3CA mutations had a shorter median PFS than wild-type." (PMID 36176758, 2022). "In breast cancer, immune response was lower in PIK3CA-mutated tumors compared with wild type tumors." (PMID 36672784, 2022). "For example, PIK3CA E545K / E542K is the second most recurrent PIK3CA mutation in breast cancer, but it also occurs highly in colon adenocarcinoma, lung adenocarcinoma, and bladder urothelial carcinoma." (PMID 36551512, 2022). "This was similarly observed in the SOLAR-1 study, where PIK3CA-mutated breast cancer, detected using plasma ctDNA, was associated with a better response to alpelisib plus fulvestrant than the fulvestrant arm." (PMID 35805046, 2022). "It has been reported that PIK3CA mutations occur in approximately 30% of human solid tumors, including colorectal cancer, glioblastoma, gastric cancer, breast cancer, and lung cancer, and so forth." (PMID 35778737, 2022). "We show for the first time that allelic expression imbalance between PIK3CA’s mutant and wild-type alleles is common and prognostic in breast cancer." (PMID 35676284, 2022). "PIK3CA mutations are prevalent in breast cancer, with 35.7% (2261/6338) of tumors carrying the mutations, most common in estrogen receptor-positive breast cancer." (PMID 35402264, 2022). "For example, in breast cancer, the region encoding PIK3CA was significantly overrepresented in mutations, compared to the expected mutation burden predicted from the models based on CA and RT profiles (92 SNVs observed vs. 44 expected; FDR = 9.2 x 10−4)." (PMID 35947558, 2022). "In summary, extended follow-up from the phase II BYLieve study support the sustained benefit of alpelisib plus endocrine therapy in patients with HR-positive, HER2-negative, PIK3CA-mutated advanced breast cancer." (PMID 35348782, 2022). "Our results demonstrated that PI3K inhibitors showed prominently therapeutic efficacy in PIK3CA-altered HPVneg HNSCC while CDK4/6 inhibition has also been proven to improve the response to PI3K inhibitors in PIK3CA-mutated breast cancers." (PMID 35546399, 2022). "This is also in line with what was observed in another clinical trial (NCT01277757), enrolling advanced breast cancer patients with PIK3CA/Akt1 or PTEN mutations or loss, where the AKT inhibitor, MK-2206, showed limited clinical activity." (PMID 35337095, 2022). "The deregulation of this pathway is implicated in the progression of solid cancers, particularly those harboring mutation in PIK3CA gene, such as ovarian, colon and breast cancers." (PMID 35408658, 2022). "The Mcl-1i + PI3Kβ/AKTi combination was effective across a panel of breast cancer cell lines with PIK3CA and PTEN mutations, and delivered increased anti-tumor benefit in vivo." (PMID 36241868, 2022). "Our method’s main advantage is that it is a non-invasive method for identifying PIK3CA mutations in breast cancer suitable for avoiding invasive damage when surgery and biopsy are inconvenient." (PMID 35719907, 2022). "PIK3CA mutation is the most common alteration of this pathway linked to breast cancer, with ≥80% of mutations occurring within the helical (E542K and E545K) and kinase (H1047R) domains of p110α [1,]." (PMID 35016012, 2022). "The hotspot mutation H1047R in oncogenic PIK3CA was often detected in breast cancer, which enhances the enzymatic activity of PI3K and activates the AKT/mTOR signaling pathway." (PMID 35966080, 2022). "A patient with metastatic HR+/HER2− breast cancer, e.g., who progressed following paclitaxel treatment had increased mutant allele fractions of PIK3CA, BMI1, and SMC4." (PMID 36141326, 2022).
breast cancer (continued). "According to SOLAR-1 (NCT02437318) and BYLieve (NCT03056755, cohort A) trials, breast cancer patients carrying PIK3CA mutations who received any CDK4/6 inhibitor and fulvestrant treatment followed by alpelisib had a better prognosis." (PMID 36058938, 2022). "Genetic alteration of the PIK3CA gene, encoding the catalytic subunit of the PI3Kα isoform, occur in 36% of breast cancer patients." (PMID 35673573, 2022). "Aim of this study was to determine the prevalence of PIK3CA-mutations in a cohort of early stage breast cancer patients and the association to the course of disease." (PMID 36279023, 2022). "Multiple clinical studies revealed that the prevalence of PIK3CA mutations is 18%–46.5% in breast cancer." (PMID 38089455, 2022). "For example, activating mutations in EGFR are frequent in relapsed lung adenocarcinoma, BRAF is often mutated in melanoma, and PIK3CA is often mutated in various entities, including luminal breast cancer." (PMID 35625984, 2022). "Focussing on known breast cancer driver genes, we identified clonal mutations in PIK3CA and MAP2K4 in ML10_Abr, and a clonal mutation in FRMPD2 in ML1_Abr." (PMID 35053458, 2022). "Mutation in PIK3CA occurs in approximately 25% of breast cancer, and it is reported as a driver of this disease." (PMID 35495618, 2022). "The PIK3CA mutation rate is 30–40% in ER-positive invasive ductal carcinoma and 7% in pure mucious breast cancer." (PMID 35799256, 2022). "A recent review by Brandao and coworkers critically analyzes clinical trials with PI3K inhibitors and suggests KRAS mutations among potential biomarkers for resistance in PIK3CA-mut breast cancer." (PMID 35719951, 2022). "We describe the available biological and clinical evidence of PIK3CA mutations in breast cancers other than HR+/HER2-, summarizing clinical trials investigating PI3Ki in these subtypes." (PMID 36579519, 2022). "The detection of phosphatidylinositol-3 kinase catalytic alpha (PIK3CA) gene mutations in breast cancer is a key step to design personalizing an optimal treatment strategy." (PMID 35719907, 2022). "PIK3CA mutation triggers centrosome amplification and increases tetraploidization-tolerance in breast cancer cells." (PMID 35563449, 2022). "This PIK3CA mutation found in patients with breast cancer has a much lower response to tyrosine kinase inhibitors, such as lapatinib and trastuzumab." (PMID 36109789, 2022). "In a study on 458 samples of breast cancer, 151 samples had PIK3CA mutations (33.0%), 10 samples had PIK3R1 mutations (2.2%), and 283 samples had PIK3R1 underexpression (61.8%)." (PMID 35482141, 2022). "Phosphatidylinositol-4,5-bisphosphate 3-kinase catalytic subunit alpha (PIK3CA) mutations and Akt activation by phosphorylation (pAkt) are often detected in many cancers and especially at high frequencies in breast cancer." (PMID 35399416, 2022). "Especially for PIK3CA H1047R, a driver mutation in breast cancer, was also reported as a neoantigen source in gastric cancer." (PMID 35387130, 2022). "PIK3CA amplification is a frequent genetic event in various cancers such as lung squamous cell carcinoma, cervical squamous cell carcinoma, esophageal adenocarcinoma, breast carcinoma, and is usually mutually exclusive with PIK3CA mutations." (PMID 35402264, 2022).
breast cancer (continued). "Clinical efficacy was observed in patients with ovarian cancer (PIK3CA E545K mutation) and breast cancer (PIK3CA H1047R and Akt1E17K mutations)." (PMID 33723724, 2021). "MK2206 has displayed prominent antitumour activity in preclinical breast cancer models with PIK3CA and/or PTEN mutations both on its own, or when enhanced with endocrine therapies." (PMID 33810522, 2021). "We generated isogenic knockin mutants of each PIK3CA hotspot mutation in HER2-amplified breast cancer cells using adeno-associated virus-mediated gene targeting." (PMID 34344439, 2021). "Activating the PIK3CA gene mutation is the most common alteration in breast cancer with different frequency among various subtypes identified more than 70% in luminal tumors, 39% in hormone-independent HER2+, and approximately 9% in TNBC." (PMID 34298639, 2021). "It is known to be frequently altered in human cancers, especially in breast cancer, with its overexpression associated with the activation of oncogenes such as PIK3CA and MTOR and inactivation of tumor suppressor genes such as PIK3R1 and PTEN." (PMID 34415239, 2021). "High PIK3CA expression was associated with in vitro sensitivity of breast cancer cell lines to pictilisib." (PMID 34038440, 2021). "In breast cancer, an association between somatic mutations in PIK3CA and the positive expression of the estrogen receptor (ER) has been reported." (PMID 34287479, 2021). "In Chinese breast cancer patients, PIK3CA somatic mutations were detected in 14% and 43% of the patients harboring germline BRCA1/BRCA2 mutations (vs. wild type carriers), respectively." (PMID 34287479, 2021). "PIK3CA mutations/amplifications were by far the most common ESCAT alternations identified from Taiwanese breast cancers (37.1% for all alternations and 35.8% for mutations, Tier IA for PIK3CA mutation)." (PMID 33632156, 2021). "Alpelisib, an orally administered PIK3CA inhibitor, has been approved by the FDA to treat breast cancers with PIK3CA mutations." (PMID 34625531, 2021). "The most common genetic alterations of PIK3CA were observed also in metastatic breast cancer biopsies, confirming the clonal character of these mutations." (PMID 34298731, 2021). "PIK3CA mutations have been found in approximately 30% of human cancers, including breast cancer, ovarian cancer, colon cancer, and prostate cancer." (PMID 33987081, 2021). "We conducted prospective clinical sequencing of 1923 Chinese breast cancer patients and illustrated the clinical significance of PIK3CA mutations in locally advanced and advanced HER2+ cohort." (PMID 34842356, 2021). "Increased INPP4B mRNA and protein expression was detected in 14–40% of breast cancers associated with ER-positivity and mutant PIK3CA expression." (PMID 34035258, 2021). "PIK3CA gene is frequently mutated in breast cancer, with PIK3CA H1047R as the hotspot mutation reported in TNBC." (PMID 34415239, 2021). "In a recent SAFIR02 study, 22% of the total population and 28% of patients with HR+ breast cancer featured a PIK3CA mutation." (PMID 33842357, 2021). "Because almost 40% of ER+ breast cancers harbor PIK3CA mutations, combination therapies using alpelisib or taselisib with endocrine therapies have been extensively tested in clinical trials." (PMID 33809714, 2021). "The experiments were performed on the MCF7 breast cancer cells that are characterized by the unique coding mutation in the PIK3CA gene." (PMID 33922925, 2021). "PIK3CA mutations and Akt activation by phosphorylation (pAkt) are commonly detected in various cancers, but its frequency is found to be high in breast cancer." (PMID 34944840, 2021). "About 20%–50% of breast cancers harbour PIK3CA mutations, of which 35% are hormone receptor positive (HR+) and 25% are HER2+ subtypes." (PMID 34842356, 2021).